PIEZO1 (piezo type mechanosensitive ion channel component 1 (Er blood group))
Diseases named in the same sentence as PIEZO1 in open-access papers (continued):
Sharing a sentence is not in itself a finding about the gene and the disease.
tumor (continued). "To emphasize the effectiveness of Piezo1 as a novel drug target for disease intervention, we summarize its physiological roles in different tissues and organs and its expression in different tumor tissues." (PMID 40061015, 2025). "Matrix stiffness has been documented to regulate the expression of key tumor genes through various signaling pathways, including the integrin β1/Piezo1 activation/Ca2+ influx pathway, RhoA/ROCK pathway, YAP-POSTN-integrin mechanotransduction signaling, and YAP/TEAD4/ACADL axis." (PMID 40867005, 2025). "Piezo1 promotes T cell adhesion and migration, facilitating their accumulation at tumor sites." (PMID 41195420, 2025). "Moreover, the MCF-7 cell line was also employed in the first study regarding Piezo2 expression, with opposite results to Piezo1 regarding the prognostic significance, suggesting a relationship between Piezo2 and the least aggressive neoplasms." (PMID 39001475, 2024). "In the future, it might be important to alter the regional activity of Piezo1 ion channel in tumor, and the discovery of clinically applicable Piezo1 agonist or antagonist might be of great significance in clinical practice." (PMID 38463518, 2024). "Inhibition of Piezo1 has been shown to suppress cancer cell proliferation, suggesting that targeting Piezo1 may have therapeutic potential in inhibiting tumor growth." (PMID 38379701, 2024). "In addition, Piezo1 has been found to work in other tumor treatments or in combination with other anti-tumor drugs." (PMID 38690080, 2024). "Optimization of drug delivery systems could also be used to effectively deliver Piezo1 inhibitors to CNS tumor sites through nanotechnology or other advanced drug delivery systems, thereby improving the precision and effectiveness of treatment." (PMID 39539343, 2024). "Overall, Piezo1 has a potentially important role as a target for tumor treatment." (PMID 38690080, 2024). "Specifically, there may be a potential positive feedback link between Piezo1 and actin, which together promote the polarization of macrophages to M1 type and ultimately contribute to tumor therapy." (PMID 38690080, 2024). "The Piezo1/integrin β1 signaling axis contributes significantly to the targeting efficiency of R11 peptides in both orthotopic tumor models and clinical samples, demonstrating satisfactory tumor‐targeted imaging efficiency both in vivo and in vitro." (PMID 39258781, 2024). "Similarly, Piezo1 acts as an oncogene in pancreatic cancer progression, and its activation regulates the cancer-tumor microenvironment interaction to accelerate the growth of pancreatic cancer tumors." (PMID 38690080, 2024). "Therefore, the effect of Piezo1 on the homing efficiency of MSCs and tumor progression is an interesting direction to explore." (PMID 38690080, 2024). "Piezo1 can inhibit the recruitment and amplification of MDSCs to suppress tumor development." (PMID 38690080, 2024). "However, the most pronounced increase was seen in the EPI-MES plasticity marker, SERPINE1, where expression in the TCGA tumor samples additionally correlated with PIEZO1 in an EPI-MES score-dependent manner." (PMID 38632473, 2024). "Several studies have shown that Piezo1 can help tumor cell metastasis by promoting EMT." (PMID 38690080, 2024). "The role of PIEZO1 in tumor invasion and metastasis has received growing attention." (PMID 38494915, 2024). "Given that ERK1/2 and p38 MAPK are involved in cell proliferation, their activation by Piezo1 may be one of the mechanisms promoting tumor cell proliferation." (PMID 38690080, 2024). "Moreover, Piezo1 regulates tumor progression by affecting the recruitment, activation, and differentiation of multiple immune cells." (PMID 38690080, 2024). "In the first case, Piezo1 was mechanically activated, then it triggered endothelin release from the stimulated cell, followed by activation of endothelin A receptors in the neighboring tumor cells." (PMID 36837670, 2023).
tumor (continued). "Conventionally recognised as a mechanosensor at the context of tumour microenvironment, PIEZO1's interaction with α‐smooth muscle actin (SMA) cancer‐associated fibroblasts (CAFs)‐hybrid cells exhibiting characteristics of both fibroblasts and smooth muscle cells‐raises intrigue." (PMID 37983931, 2023). "This is a positive feedback process, and activation of Piezo1 may be central to exacerbating tissue sclerosis and promoting tumor progression." (PMID 37366640, 2023). "The aberrant expressions of Piezo1/2 are either positively or negatively correlated with patient survival in a variety of cancer types, implicating that Piezo1/2 show either oncogenic or tumor suppressive functions, likely depending on cancer type and subtype." (PMID 37864030, 2023). "So far, Piezo1 expression is correlated with tumor stage, grade, and size and is increased in ≥pT2." (PMID 36837670, 2023). "In addition, we depleted PIEZO1, a well‐established mechanosensitive channel, in tumor cells and observed that PIEZO1 depletion abrogated confinement‐induced upregulation of IGFBP1 mRNA and protein levels." (PMID 37296072, 2023). "Furthermore, we established a subcutaneous xenograft tumor model using CCSCs to further characterize the tumorigenic role of Piezo1 in vivo." (PMID 37306789, 2023). "Consequently, angiogenesis, tumor growth, and, finally, invasion with metastasis are endorsed by Piezo1." (PMID 36837670, 2023). "The authors have shown that the Piezo1 channel is necessary for tumor growth in vitro and in vivo." (PMID 37366874, 2023). "When Piezo1 expression is upregulated, the proliferative feature of the tumor is promoted." (PMID 36837670, 2023). "Together, the roles of Piezo1/2 as mechanosensors are crucial in tumor progression." (PMID 37864030, 2023). "We further confirmed that Anti‐PIEZO1‐MMAE could very efficiently kill tumor cells via inducing cell cycle arrest and apoptosis, which was highly dependent on the dosage of Anti‐PIEZO1‐MMAE and PIEZO1 expression levels." (PMID 35608274, 2022). "Knockdown of PIEZO1 can inhibit cell migration and tumor growth." (PMID 35747124, 2022). "The opening of the Piezo1 calcium channel is a dynamic process that may change throughout tumor development." (PMID 35454942, 2022). "It is well known that adherent tumor cells can sense mechanical cues through Piezo1." (PMID 35510498, 2022). "The distinct correlation between PIEZO1 and prognosis of tumor patients was explored by GEPIA2." (PMID 35747124, 2022). "Thus, our results contribute to a more comprehensive understanding of the immunopathological process of DC Piezo1-directed T cell differentiation in the tumor microenvironment." (PMID 35993548, 2022). "All these results indicate that Piezo1 knockdown inhibited tumor growth in vivo." (PMID 35461277, 2022). "Corresponding to the in vitro results, the Ki67 staining in the tumor sections of all groups revealed that Anti‐PIEZO1‐MMAE could efficiently inhibit ESCC cells propagation in vivo." (PMID 35608274, 2022). "For examples, Yoda1, a Piezo1 activator, can be used to respond to inflammatory and stiffness signals in tumors, and integrate a variety of intracellular signals to effectively direct T cell differentiation in protecting against tumor growth." (PMID 35993548, 2022). "However, there are more Foxp3+Treg cells and less IFNγ+TH1 cells, but similar TH2 and TH17 cells in Piezo1-/- compared with WT bearing-tumor mice." (PMID 35993548, 2022). "We observed changes in tumor growth in Piezo1-/- and WT mice." (PMID 35993548, 2022). "It has been reported that Yap may regulate the expression and function of Piezo1 in tumor cells to regulate its proliferation and migration." (PMID 35464728, 2022).
tumor (continued). "In a pan-cancer analysis, Piezo1 is remarkably associated with innate and adaptive immune responses, inflammation, as well as the infiltration of inflammatory cells, including lymphocytes, leukocytes, and neutrophils, suggesting that Piezo1 plays an important role in tumor immunity." (PMID 36230880, 2022). "Furthermore, previous studies revealed that Piezo1 mediates these cancer hallmarks, and thus links up mechanical forces with tumor progression." (PMID 36230880, 2022). "Furthermore, the PIEZO1 antibody combined with monomethyl auristatin E (MMAE) can specifically kill PIEZO1 high‐expressed ESCC tumor cells by inducing cell cycle arrest and apoptosis." (PMID 35608274, 2022). "However, the evidence of Piezo1 in tumor immunization is still limited; thus, future studies are needed to explore the effects and mechanisms of Peizo1 on tumor immunity." (PMID 36230880, 2022). "The rate of tumor growth was significantly faster and greater in Piezo1-/- than in WT mice." (PMID 35993548, 2022). "Finally, tumor promotion effect of Piezo1 was found to exerted through recruiting and combining Rab5c to activating TGF-β signaling pathway." (PMID 35461277, 2022). "Furthermore, we tested a few other ADC candidates which were also highly expressed on tumor cell membrane; our data indicated that Anti‐PIEZO1‐MMAE had a much more significant tumor‐suppressing activity than any other ADCs." (PMID 35608274, 2022). "However, the results of studies in NSCLC showed that the down-regulation of Piezo1 expression promoted tumor migration." (PMID 36615408, 2022). "Recent studies have shown that Piezo1 can induce tumor angiogenesis in an HIF-1α-dependent manner." (PMID 36230880, 2022). "Therefore, Piezo1 plays an important role in the transvascular migration of tumor cells and provides a basis for distant metastasis of the tumor." (PMID 36112948, 2022). "As discussed for tumor cases and as already proposed for renal tumors, Piezo1 could also be, at least, a biomarker for discriminating the aggressiveness of cardiac fibrosis and, at most, a beneficial therapeutic target." (PMID 35897650, 2022). "MC38-OVA tumor cells were implanted subcutaneously in WT and Piezo1-/- mice." (PMID 35993548, 2022). "Therefore, the discovery of Piezo1 provides a new insight for elucidating the mechanism of tumor progression under a mechanical microenvironment." (PMID 36230880, 2022). "In line with the in vitro experiments, 5‐mg/kg Anti‐PIEZO1‐MMAE treatment could dramatically suppress tumor development as compared to vehicle and isotype control without any significant effect on body weight." (PMID 35608274, 2022). "Recent studies have demonstrated that the Piezo1 protein of DCs responds to inflammatory and mechanical stimulation and further regulates the differentiation of Th1 and Treg cells, to prevent tumors in the tumor microenvironment under other circumstances." (PMID 36615408, 2022). "In addition, the PIEZO1 protein phosphorylation level was different between tumor and normal tissues, while different tumors shared diverse phosphorylation sites." (PMID 35747124, 2022). "Therefore, Piezo1 modulator provides a new choice in the research of tumor immune microenvironment intervention, which takes DCs as the target to regulate T cell responses." (PMID 35993548, 2022). "Furthermore, by deleting Piezo1 in an animal model, they observed inhibition of tumor growth and prolonged animal survival, demonstrating the necessity of Piezo1 for aggressive tumor behavior." (PMID 35897650, 2022). "Compared with the complex tumor microenvironment, artificially controlled conditions in vitro are suboptimal, and therefore, additional studies are required to investigate the consistency of the effects of Piezo1 in vivo and in vitro." (PMID 35701561, 2022).
tumor (continued). "By injecting B16 cells (shPiezo1and shNC fluorescently labeled) into mice and collecting lung tissue for frozen sectioning after 6 hours, we definitely found that the number of tumor cells which penetrated the blood vessels was 50% lower in the Piezo1-silenced group than that in the control group." (PMID 36112948, 2022). "Therefore, we examined the effect of US treatment on Piezo1 expression and its spatial distribution in tumor cells." (PMID 34589605, 2021). "In peritoneal metastatic GC mouse model, we found that silencing Piezo1 could notably suppress peritoneal metastatic tumour growth, block EMT process and angiogenesis." (PMID 33439514, 2021). "Piezo1 has not been directly linked to the colonization of distant tumor sites following cancer cell dissemination." (PMID 34831037, 2021). "Moreover, we find an increase in expression levels of Piezo1 in mechanically‐stressed tumor cells, which would synergize with elevated level of calpains in tumor cells." (PMID 34589605, 2021). "After infection by si‐Piezo1, the number and growth of tumours were observed in abdominal cavity." (PMID 33439514, 2021). "In peritoneal metastatic GC mouse model, Piezo1 knockdown could notably inhibit peritoneal metastatic tumour growth, block EMT process and angiogenesis." (PMID 33439514, 2021). "Piezo1 is widely expressed in a variety of cells and tissues, including tumor cells." (PMID 32152662, 2020). "In this study, we tested, whether Piezo1 is still active in the presence of an acidic pHi and/or pHe, conditions that resemble the acidic tumor core." (PMID 32116794, 2020). "Taken together, these data indicate that PIEZO1 may provide a physical means for the transfer of mechanical forces, through which the tumour cells are able to directly respond to ECM changes to regulate gene transcription." (PMID 32999349, 2020). "In addition, further in vivo experiments demonstrated that the suppression of Piezo1 gene expression enhanced tumor growth of such cells in immunocompromised mice." (PMID 32635333, 2020). "The Piezo1 upregulation was directly correlated with tumor stage and size." (PMID 32635333, 2020). "However, Piezo1 expression varies across organs, and it response to different signals and mechanical forces is highly context-dependent, making mechanically mediated Piezo1 signalling during tumour metastasis extremely complex." (PMID 41437911, 2026). "Therefore, targeting Piezo1 can orchestrate a multi-dimensional anti-tumor immune response." (PMID 41607548, 2026). "However, strategies targeting Piezo1 for tumour immunotherapy face significant challenges." (PMID 41437911, 2026). "Consequently, Piezo1 acts both as a “sensor” of external mechanical cues and as a “threshold setter” that determines pro- or anti-tumor outcomes, with its function governed by the degree of spatial confinement, signal strength, and the extent of cell-shape remodeling." (PMID 40821847, 2025). "Additionally, such differences may arise from intratumoral heterogeneity and variations within the tumor microenvironment, where distinct cellular subpopulations may differentially express PIEZO1 at the mRNA and protein levels." (PMID 40724850, 2025). "Finally, the development of targeted inhibitors or modulators of PIEZO1 could represent a promising direction for therapeutic intervention, particularly in patients with aggressive tumor phenotypes and poor prognosis." (PMID 40724850, 2025). "In tumor cells, Piezo1-mediated Ca2+ signaling promotes cytoskeletal remodeling, epithelial–mesenchymal transition, YAP/TAZ activation, and angiogenesis; concomitantly, Piezo1 drives cancer-associated fibroblast activation and ECM remodeling, collectively reinforcing invasion and therapy resistance." (PMID 40821847, 2025). "Moreover, PIEZO1 depletion increased tumor cell death in confining pores." (PMID 41390768, 2025).
tumor (continued). "Simultaneously, knockdown of integrin β1 or Piezo1 distinctly attenuated high stiffness stimulation‐caused glucose consumption and lactate production, indicating that matrix stiffness enhances glycolytic level of HCC cells, and thereby promotes tumour growth and proliferation." (PMID 41292194, 2025). "Notably, under non-tumor or acute infection conditions, Piezo1 may enhance type I interferon production by DCs, thereby activating NK cells and cytotoxic T lymphocytes (CTLs)." (PMID 40821847, 2025). "Moreover, abnormal expression of Piezo1 may enhance the immune evasion capacity of tumor cells by modulating immune cell function, further impacting tumor immune escape mechanisms." (PMID 40821847, 2025). "Additionally, Piezo1 supports optimal T-cell activation during tumor challenges." (PMID 40977743, 2025). "Therefore, Piezo1 is a promising tumor biomarker and therapeutic target." (PMID 38690080, 2024). "Additionally, Piezo1 is considered a potential tumor-promoting marker and its inhibition may inhibit the progression of pancreatic ductal adenocarcinoma." (PMID 38379701, 2024). "Therefore, PIEZO1 may play a role in modulating oncogenic pathways to impact the tumor microenvironment, immune response, and, ultimately, patient outcomes." (PMID 38398074, 2024). "CD8+ and CD4+ T cells are well established as the most prominent mediators of anti-cancer immunity, so our results suggest that PIEZO1 may also have a molecular role that reflects cancer aggressiveness and the suppression of anti-tumor immunity in HR-negative breast cancer." (PMID 38398074, 2024). "PIEZO1 may participate in these processes to reduce T cell infiltration into the tumor." (PMID 38398074, 2024). "As a result, the Piezo1 channel could be a potential target for tumor therapy." (PMID 38690080, 2024). "Therefore, Piezo1 has excellent potential as an anti-tumor target." (PMID 38690080, 2024). "Knockdown of Piezo1 decreases endogenous β1 integrin affinity at the plasma membrane, inhibits cell adhesion, and promotes cell migration in a non‐integrin‐dependent manner, which is responsible for increased tumor cell migration and metastasis in small‐cell lung carcinoma." (PMID 37366640, 2023). "Therefore, targeting either PIEZO1 or CTGF could represent a viable strategy for obstructing tumour progression and peritoneal metastasis in GC patients." (PMID 37983931, 2023). "Therefore, the discovery of Piezo1, which links-up physical factors with biological properties, provides a new insight for elucidating the mechanism of tumor progression under a mechanical microenvironment, and suggests its potential application as a tumor marker and therapeutic target." (PMID 36230880, 2022). "Moreover, Piezo1’s early closing state and intracellular calcium overload formation may be a key link that leads to the final tumor-infiltrating macrophages." (PMID 35454942, 2022). "Therefore, it is possible that suspended tumor cells might sense fluid shear stress via Piezo1 channel, which might further affect histone acetylation and nuclear size." (PMID 35510498, 2022). "Furthermore, as will be summarized in the following sections, recent studies have shed light on the role of Piezo1 as a mechanical force sensor and transducer in various cancer hallmarks, linking up the mechanical sense with the biological properties of tumor cells." (PMID 36230880, 2022). "Piezo1 plays a crucial role in the regulation of tumor growth and metastasis, but it has different effects on the function and differentiation of innate and adaptive immune cells, which is different from the supervisory mechanism of Piezo1 on tumor cells themselves." (PMID 36615408, 2022).